MTOR (mechanistic target of rapamycin kinase)
Diseases named in the same sentence as MTOR in open-access papers (continued):
Sharing a sentence is not in itself a finding about the gene and the disease.
tumor (continued). "In summary, our study indicates that METTL14 is the main regulator for the abnormal m6A modification in GC and METTL14 suppresses GC cell progression and aggression by deactivating the PI3K/AKT/mTOR pathway and the EMT pathway as a tumor suppressor." (PMID 33314339, 2021). "For example, the KEGG pathway “mTOR signalling” forms a network whose nodes are significantly upregulated in subtype-1 tumours and are previously linked to oncogenesis, but in this case, we suggest that this is likely only correct in subtype-1 tumours and not in subtype-2 tumours." (PMID 34506537, 2021). "Transcriptome profiling studies performed in DUSP9-silenced SW480 cells reported an enrichment of several signaling pathways related to tumor growth and metastasis, such as ERK, JNK, WNT, AKT/mTOR and ERBB." (PMID 34768967, 2021). "As AMPK downregulates mTORC1 in different kinds of tumours, we also studied the role of AMPK on V600EBRAF-induced mTOR activation." (PMID 34204950, 2021). "SNORA23 is directly affected by the PI3K/AKT/mTOR cascade and acts as a tumor suppressor in HCC; thus, we next aimed to determine the effect of SNORA23 on downstream regulators of PI3K/AKT/mTOR signaling by using Western blot." (PMID 33710804, 2021). "The tumor suppressor PTEN, an upstream negative regulator of mTOR, has been proved involved in the autophagy process in the occurrence and development of the malignant tumor." (PMID 33413409, 2021). "Mechanism assays indicated that miR-124-3p played a tumor suppressor by directly interacting with PCDH8 and inhibiting the activation of PI3K/AKT/mTOR signaling pathway." (PMID 34234863, 2021). "Aloin significantly upregulated the phosphorylation levels of mTOR and AKT while promoting autophagy, inhibiting tumor cells, and downregulating PI3Kα." (PMID 34819120, 2021). "Downregulated Robo1 by lentivirus-based miR-29a overexpression is involved in the inactivation of PI3K/AKT/mTOR axis, leading to impeded HCC cell proliferation, migration, and invasion in vitro and alleviated HCC tumor growth and metastasis in vivo." (PMID 33803804, 2021). "Besides increased VEGF expression, overactivation of the PI3K/mTOR pathway has also been associated with increased expression of other immunosuppressive cytokines and chemokines, such as CCL20, CXCL1, IL-6, IL-23, and IL-10, and increased expression of PD-L1 on the surface of tumor cells." (PMID 33922556, 2021). "A high expression of amino acid transporters in tumor cells is also critical for maintaining tumor redox homeostasis by regulating the intracellular GSH levels, ER stress, UPR signaling, and mTOR-mediated antioxidant defense." (PMID 33401748, 2021). "Salmonella treatment inhibited AKT/mTOR signaling pathways, which further reduced the expression of MMP9 in the mouse tumor models." (PMID 33996789, 2021). "Similar to these published reports, in this study, we too observed that NSCLC patient tumor tissues were positive for PI3K, AKT3, p-AKT3, mTOR, and p-mTOR proteins by IHC." (PMID 33833996, 2021). "Treatment with rhein significantly suppressed mTOR and the expression of its downstream effectors, p70S6K and 4EBP1, in CRC cells and xenograft tumor tissues." (PMID 33946531, 2021). "Various signaling pathways are associated with chronic inflammation, including the MAPK, AKT, mTOR, STAT3, and/or NF-κB pathways, and can potentially lead to tumor promotion." (PMID 34950252, 2021). "Through TGF-β/mTOR/HIF-1 signalling, high levels of CD39 and CD73 were detected in MDSCs undergoing metabolic reprogramming in tumour-bearing mice)." (PMID 34685679, 2021). "LKB1 is a tumor suppressor involved in many cellular functions surrounding cell cycle control, energy, metabolism, and polarity which it regulates through AMPK/mTOR signaling." (PMID 34063609, 2021). "Well-known tumor-promoting signaling pathways, such as ERK1/2, Akt, mTOR, and STAT6 are among those induced by the mentioned factors." (PMID 34071442, 2021).
tumor (continued). "Erianin efficiently decreased the tumor sizes, together with visibly reduced expression of PPT1 and phosphorylation of mTOR in the xenograft tumor tissues." (PMID 35004674, 2021). "We assessed [18F]FDG PET uptake and tumor volume in trastuzumab-sensitive and trastuzumab-resistant HER-2-overexpressing tumor xenografts after treatment for 2 and 7 days with PI3K/Akt/mTOR targeted drugs." (PMID 34113218, 2021). "We used HuCCT-1 cell xenograft model to investigate the anti-tumor effect of Tan-IIA and the role of PI3K/Akt/mTOR signaling pathway in the anti-tumor effect of Tan-IIA." (PMID 34588580, 2021). "PTEN is a well-established tumour-suppressor gene which expressed in all tissues in the body, and its main target is PI3K/AKT/mTOR pathway." (PMID 33417512, 2021). "The ssGSEA results showed that the top 20 activated pathways were basically tumor-related pathways, including immunity pathways (TGF-β), cell junctions pathway (adherens junction), and metabolism pathway (mTOR signaling pathway)." (PMID 34221955, 2021). "Immunofluorescence performed in xenograft tumors generated by UM-HMC-3A cells corroborated the primary human tumor data, and indicated that most ALDH1-positive cells also express p-mTOR." (PMID 33479203, 2021). "Recent studies have shown that circFBXW7 plays a tumor inhibitory role by reversing the expression of NEK2 and mammalian target of rapamycin (mTOR), promoting the expression of PTEN in tumors." (PMID 34112159, 2021). "While ROS is crucial for the anti-tumor function of neutrophils, ROS can also promote tumor growth by activating the NFκB and PI3K/Akt/mTOR survival signal transduction pathways in the tumor cells and by inducing angiogenesis." (PMID 34572138, 2021). "In fact, the anti-tumor functions are mediated by ropivacaine, potentially via inactivation of the IGF-1 R/PI3K/AKT/mTOR signaling pathway." (PMID 34696683, 2021). "Guo and Wang revealed the role of miR-329-3p as a suppressor of HCC cell proliferation, invasion, migration, and EMT processes as well as tumor growth by downregulating FOXK1 and inhibiting the AKT/mTOR pathway." (PMID 34307695, 2021). "Studies have also shown that multiple signal transduction pathways are involved in the regulation of tumor cell autophagy, such as AMPK, MAPK, Akt/mTOR, and other signal pathways." (PMID 34764997, 2021). "PTEN is one of the most common tumor suppressor genes, which regulates cell apoptosis and cell cycle through PI3K/Akt/mTOR signaling pathway." (PMID 33996542, 2021). "Treatment with mTOR inhibitors releases 4E-BP1, and allow it to have the tumor suppressor effect through inhibition of the translation initiation factor eIF4G, that plays an important role in cell proliferation and tumor formation." (PMID 33479203, 2021). "Immunohistochemistry (IHC) of tumor specimens showed a visible decrease in the expression of Ki67, RSK, p70S6K, mTOR, p-mTOR and N-cadherin (N-Cad), and the E-cadherin (E-Cad) expression was increased compared with control." (PMID 34094949, 2021). "Osteopontin-integrin αvβ3 interactions have also been shown to promote critical mediators of tumor cell proliferation and survival including activation of Src, ERK and PI3K/AKT/mTOR pathways." (PMID 33805598, 2021). "The majority of these alterations were related to defects in DNA repair, making tumours potentially sensitive to PARP inhibition, but frequent targetable alterations were also seen in BRAF, MTOR signalling as well as several other genes." (PMID 34647903, 2021). "An immunohistochemical study performed in 154 patients indicated that p-mTOR (Ser2448) and p-p70S6K (Thr389) were overexpressed in CRC tumor tissues compared to in normal colon tissues." (PMID 33946531, 2021). "Tumor proliferation is regulated by multiple cellular pathways, such as the PI3K/Akt/mTOR signaling pathway, and some circRNAs are involved in the regulation of tumor proliferation through these pathways." (PMID 33996542, 2021).
tumor (continued). "The PI3K/AKT/mTOR pathway is upregulated in most HNSCC cells, and it is crucial to tumor cell proliferation, differentiation, survival, and metastasis." (PMID 33802643, 2021). "In vitro, C1q displays an anti-tumor effect in SKOV3 cells by promoting apoptosis through the upregulation of the TNF-α pathway and the downregulation of the mammalian target of rapamycin (mTOR) survival pathway." (PMID 34359708, 2021). "Temsirolimus inhibited mTOR/TORC1, which was evidenced by monitoring circulating tumor cells (CTC), prostate-specific antigen (PSA) levels, progression-free survival (PFS), and overall survival (OS) times." (PMID 34452154, 2021). "The overactivation of PI3k/Akt/mTOR pathway promotes glycolysis and glucose-dependence, leading TSC1/TSC2 mutant tumor cells entering apoptosis after glucose withdraw." (PMID 33821877, 2021). "Tumor infiltration by immunocompetent cells and, consequently, the production of PD receptors, PD-L1, and PD-L2 ligands by tumor cells, are also controlled by AKT/mTOR kinases." (PMID 34681840, 2021). "Together, these results further confirm that NT-1044 and metformin inhibits tumor growth of EC, potentially via targeting of the AMPK/mTOR/S6 pathway in vivo in both obese and lean mice." (PMID 34422646, 2021). "In terms of mechanism, miR-30b-5p is reported to control tumor or disease progression by regulating autophagy, epithelial-mesenchymal transition (EMT), and mTOR signaling pathway." (PMID 34819077, 2021). "Several important genes emerged in this study that are overexpressed in BA versus WA patients in both tumor and TAS, including PIK3CA, mTOR and CD53." (PMID 34316327, 2021). "Immunohistochemistry staining of tumor tissues showed that aminoquinol treatment significantly reduced the expressions of Rb, CDK4, CDK6, PI3K, pho-AKT and pho-mTOR, as compared to the control group." (PMID 34335258, 2021). "Firstly, we used the platform GSCALite to analyze the activities of ten well-known tumor-related pathways, such as RTK, RAS/MAPK, TSC/mTOR, cell cycle, DNA damage response, EMT, hormone ER, hormone AR, PI3K/AKT, and apoptosis pathway." (PMID 34804125, 2021). "The results also showed that inhibiting the mechanistic target of rapamycin (mTOR) in the in vivo LSQ models overexpressing FGF19, was an effective way to inhibit the tumor." (PMID 34572066, 2021). "Such molecules as p-Akt, p-mTOR, p-p38, MMP-2/9, and BCL-2 were all downregulated, whereas Bax and cleaved-caspases-9 were upregulated after fucoxanthin treatment of the tumor tissues." (PMID 34440090, 2021). "In conclusion, PRKAR1B-AS2 promotes tumor growth and survival in OC via regulating PI3K/AKT/mTOR pathway." (PMID 33668685, 2021). "It has been suggested that (i) mTORC1 inhibition synergizes with ferroptosis inducers to suppress tumor growth, (ii) mTORC1 inhibition decreases GPX4 levels and (iii) RSL3 blocks mTOR activation." (PMID 34716292, 2021). "Several studies have shown that the levels of mTOR pathway-related proteins (including p70S6K, p-mTOR, PI3K, and pAkt) in RCC were significantly higher than those in normal kidney tissues, and positively correlated with tumor progression." (PMID 33746989, 2021). "For example, combined mTOR and HDAC inhibitors resulted in tumor regression in a mice xenografts models of KRAS-mutant NSCLC in vivo." (PMID 34301278, 2021). "The PI3Kγ signaling pathway activated by Akt and mTOR has the ability to stimulate C/EBPβ activation and inhibit the activation of NF-κB, which not only promotes TAM repolarization, but also inhibits tumor growth." (PMID 34683963, 2021). "The binding of IL-13 with its cognate receptor, interleukin-13 receptor subunit alpha-2 (IL-13Rα2), has a mechanistic role in tumor growth, invasion, and metastasis via phosphorylation and activation of PI3K, Akt, and mTOR proteins." (PMID 34439380, 2021). "Taken together, these findings revealed that CLTC played a pro‐tumor function by the TGF‐β and AKT/mTOR signaling pathways." (PMID 34185412, 2021).
tumor (continued). "LYN overexpression blocked the inhibition of tumor cell growth, as well as the inhibition of AKT/mTOR signaling pathway induced by miR-496." (PMID 34514167, 2021). "LAR-subtype PDTX-derived tumor cells (PDTCs) models displayed similar preferential sensitivity to bicalutamide and several PI3K/mTOR inhibitors." (PMID 34725325, 2021). "By contrast, the failure of tumor suppression by BO under PGF condition resulted in indistinctive changes in autophagy activity (expressions of the autophagy-related protein) and mTOR activity (phosphorylation of S6 and 4E-BP1)." (PMID 34658867, 2021). "We further investigated the mechanisms of radiation resistance by measuring the expression levels of certain proteins involved in tumor proliferation- and metastasis-related pathways (IL-6/STAT3, SDF-1/CXCR4, and PI3K/AKT/mTOR)." (PMID 34539883, 2021). "Inhibition of AURKA and the PI3K/mTOR pathway using alisertib and NVP-BEZ235, respectively reduced tumor burden in a 786-0 xenograft model of RCC." (PMID 34002003, 2021). "FBXW7 is a key substrate recognition subunit of the SCF complex that acts as a tumor suppressor gene by controlling the proteasome-mediated degradation of oncoproteins, such as c-MYC, MCL1, Notch1/4, cyclin E, and mTOR." (PMID 33676554, 2021). "The PI3K/AKT/mTOR pathway regulates forkhead-box type O (FOXO) transcription factors, which have a role in tumor suppression, and act in a context-dependent manner." (PMID 34831287, 2021). "PKI-587, an inhibitor targeting both PI3K and mTOR, can reduce the level of p-AKT and inhibit the proliferation and increase the radiosensitivity of tumor cells in vivo and in vitro." (PMID 34665844, 2021). "Global and single-cell tumor profiling reveal Met as a direct oncogenic target of TRIM24, leading to aberrant PI3K/mTOR activation." (PMID 34508101, 2021). "Overexpression of the PI3K/Akt/mTOR signaling pathway is common in (m)CRC, resulting in enhanced tumor growth." (PMID 34820593, 2021). "Akt and mTOR are the downstream targets of PI3K and abnormal activation often results in the over-proliferation of tumor cells." (PMID 34580235, 2021). "The reduced Robo1 is involved in the inactivation of PI3K/AKT/mTOR axis, leading to an impeded HCC cell proliferation, migration, and invasion in vitro and HCC tumor growth and metastasis in vivo." (PMID 33803804, 2021). "The AKT/PI3K/mTOR signaling axis is usually antagonized by the product of phosphatase and tensin homolog gene (PTEN), a tumor suppressor gene that is downregulated in CD4+ TCL as well." (PMID 33969027, 2021). "In a word, MG and honokiol suppress the proliferation, migration, and invasion of tumor cells and promote apoptosis as well as autophagy by regulating MAPK, NF-κB, HIF-α, PI3K/Akt/ERK/mTOR, and Wnt/β-catenin signaling pathways." (PMID 33815113, 2021). "Our further exploration revealed that hsa_circ_0028861 regulated the expression of five target miRNAs, and participated in some tumor-related signal pathways such as integrin, VEGF, PI3K/Akt, and mTOR." (PMID 34367259, 2021). "They demonstrated that tumor suppressor PTEN, an upstream negative regulator of mTOR, as a critical mediator of YAP in mTOR regulation." (PMID 33413409, 2021). "Rhein treatment also downregulated p-mTOR, p-p70S6K, HSF1, and cyclin D1 in tumor tissues, which further confirmed that rhein suppressed CRC cell growth by inhibiting the mTOR signaling pathway." (PMID 33946531, 2021).
tumor (continued). "In conclusion, PRKAR1B-AS2 promotes tumor growth and confers chemoresistance by modulating the PI3K/AKT/mTOR pathway." (PMID 33668685, 2021). "Everolimus, also a mTOR inhibitor, reduces the expression of VEGF in tumor-derived mouse ovarian carcinoma and in gastric cancer cells in vitro." (PMID 33925400, 2021). "In conclusion, our results indicate that CK-3 blocks the PI3K/AKT/mTOR and MAPK/ERK signaling pathways and exerts an anti-tumor effect on Hep3B and Bel7402 cells." (PMID 34395292, 2021). "All these results indicated that QFG can inhibit activation of the mTOR signaling pathway to inhibit the progression of EMT and autophagy in CRC tumor." (PMID 34887935, 2021). "Growth factor receptors interact and activate downstream PI3K/AKT/mTOR axis with subsequent transcriptional activation of FAS expression and it is critical for aerobic glycolysis and tumor growth." (PMID 33763366, 2021). "Immunofluorescence staining results of mice tumor further proved that activated p-AKT and p-mTOR were decreased following BI853520 treatment compared to controls." (PMID 35201437, 2021). "The immunoblotting data also showed that the phosphorylation proteins downstream to PI3K including mTOR, AKT, and S6RP decreased in tumor tissues with XH30 alone and in combination with TMZ." (PMID 34899305, 2021). "As an inhibitor of the mTOR pathway, RAD001 can inhibit the phosphorylation of 4EBP1, thus preventing the synthesis of tumour‐related proteins." (PMID 34120414, 2021). "β-Elemene was proved to effectively inhibit the viability of various tumor cells, including human NSCLC A549 cells, gastric cancer MGC803 and SGC7901 cells, and renal-cell carcinoma 786-0 cells by suppressing the PI3K/AKT/mTOR signaling pathway." (PMID 33801899, 2021). "This includes inhibition of the retinoblastoma (RB1) and protein phosphatases 2A (PP2A) tumor suppressors and activation of oncogenic AKT and mTOR." (PMID 34199469, 2021). "It has been shown that the tumor suppressor PTEN, located on chromosome 10, is the primary PI3K/Akt/mTOR negative regulator, which directly inhibits the action of PI3K." (PMID 34452154, 2021). "KRAS mainly activates the PI3K/AKT/mTOR and BRAF/MEK/ERK pathways and activates inflammatory pathways such as the NFκB signaling pathway, which is required for tumor maintenance and malignant transformation." (PMID 34336638, 2021). "Nevertheless, both suppression of the AKT/mTOR cascade and upregulation of Cx43 demonstrated a possible link among downmodulation of IDO, an increase in T cell infiltrates, and T cell-induced tumor apoptosis, particularly by CD8+ T cells." (PMID 34829795, 2021). "Some studies have demonstrated that a further increase in mTOR activation was identified in advanced HCC and in larger tumours." (PMID 34419152, 2021). "For instance, the combined use of mTOR inhibitors, IGF1R inhibitors, and ARS-1620 significantly enhanced tumour regression with low toxicity compared to combined MEK inhibitors or ARS-1620 alone in a series of KRAS-driven mouse lung cancer models." (PMID 34776511, 2021). "6-shogaol shows anti-tumor effect in cervical carcinoma by triggering the mitochondrial pathway of apoptosis and downregulating the PI3K/AKT/mTOR pathway." (PMID 34575981, 2021). "As one of the most studied and well-described pathways in tumor oncogenesis, PI3K/Akt/mTOR appears to play a crucial role in urothelial cancer cell growth and survival." (PMID 33451055, 2021). "The key determinants of the tumor-supportive microglia phenotype were the proteins of the MAPK, STAT, TGFβ, NFKB, PI3K, mTOR and integrin signaling pathways." (PMID 34566949, 2021). "The mTOR molecule and HIF-1α are involved in the formation of local tumor progression and distant metastasis." (PMID 33802643, 2021).